PCDH19 (protocadherin 19)
Diseases named in the same sentence as PCDH19 in open-access papers (continued):
Sharing a sentence is not in itself a finding about the gene and the disease.
Dravet syndrome (25 papers, 2009 to 2026). "The phenotype can resemble Dravet syndrome and according to some studies, PCDH19 variants are found in 25% of SCN1A-negative females exhibiting features of Dravet syndrome." (PMID 34842787, 2021). "De novo variants in genes that mediate synaptic transmission such as SCN1A and PCDH19 are often associated with Dravet syndrome." (PMID 34095830, 2021). "A novel PCDH19 p.D377N mutation was identified in one SCN1A-negative female patient with Dravet syndrome and a known PCDH19 p.N340S mutation in a female non-Dravet syndrome patient." (PMID 22848613, 2012). "A de novo PCDH19 missense mutation together with an inherited TSPYL4 missense variant were identified in a patient with Dravet syndrome." (PMID 22848613, 2012). "SCN1A-negative Dravet syndrome patients and patients with phenotypes resembling Dravet syndrome were checked for PCDH19 and TSPYL4 mutations." (PMID 22848613, 2012). "Regarding Dravet Syndrome, screening for PCDH19 mutations should be performed for female patients when analysis of SCN1A (including a method searching for SCN1A micro-rearrangements) is negative." (PMID 21053371, 2011). "The differences in the MRI scans of SCN1A and PCDH19 mutations have been documented in Dravet syndrome with initial normal brain MRI scans that eventually progressed to cortical or cerebellar atrophy, cortical dysplasia, and temporal lobe abnormalities at 2–3 years." (PMID 34833120, 2021). "Clinical features associated with PCDH19 mutations may overlap with Dravet syndrome." (PMID 38891919, 2024). "LEV can effectively alleviate seizures in eyelid myoclonia of Jeavons syndrome, Dravet syndrome with mutation of SCN1A, and PCDH19 Girls Clustering Epilepsy." (PMID 37880614, 2023). "In PCDH19 and Dravet syndrome, it has been well demonstrated that the duration and frequency of seizures directly impact brain development, demonstrating the importance of early and effective treatment, which can have a significant impact on prognosis." (PMID 36004035, 2022). "Pcdh19 mosaic mice showed delayed growth in the transition between childhood and adulthood, when circuits undergo intense remodeling, and a similar phenotype was observed in Dravet syndrome mouse models in concomitance with seizure onset." (PMID 36997609, 2024). "However, Dravet syndrome, childhood epilepsy characterized by drug-resistant seizures and episodes induced by fever such as PCDH19, was approved in 2018 as part of the second-line drug regimen." (PMID 36004035, 2022). "PCDH19-CE is characterized by a variable phenotypic spectrum that ranges from benign focal epilepsy with normal intelligence to severe generalized/multifocal epilepsy, resembling Dravet syndrome." (PMID 34201522, 2021). "PCDH19 mutations were initially thought to only affect females, however, in 2009, Depienne and colleagues described a SCN1A-negative male diagnosed with “Dravet syndrome”, as having a de novo deletion on chromosome Xq22.1 that spanned the entire PCDH19 gene." (PMID 29892053, 2019). "Since the PCDH19 and Dravet syndrome phenotypes show many similarities, testing a cohort of SCN1A-negative, male Dravet syndrome patients for mosaic PCDH19 pathogenic variants could give more insight in the true incidence." (PMID 28669061, 2017). "Given the clinical similarities involving age at seizure onset and fever sensitivity shared by PCDH19-GCE and Dravet syndrome, we investigated whether a similar association between ID severity and age at seizure onset has been demonstrated in the Dravet literature." (PMID 29892053, 2019). "We have previously reported that the similarity between PCDH19 and SCN1A clinical spectra comprises Dravet syndrome; now, we show that it also extends to that of GEFS+." (PMID 21053371, 2011).
Dravet syndrome (continued). "Summary of clinical characteristics of 18 patients with Dravet syndrome and 1 PCDH19-positive patient not grouped under Dravet syndrome." (PMID 22848613, 2012). "The high frequency of patients with PCDH19 found in this study justifies the molecular testing of this gene in SCN1A-negative patients, especially females, diagnosed as having Dravet syndrome." (PMID 19214208, 2009).
Epileptic encephalopathy (23 papers, 2009 to 2025). A condition in which epileptiform abnormalities are believed to contribute to the progressive disturbance in cerebral function. "Previous publications revealed the association of X-inactivation and PCDH19-related epileptic encephalopathy with skewed X-chromosome inactivation as a potential protective factor." (PMID 36970538, 2023). "PCDH19 mutations cause a neurodevelopmental syndrome named epileptic encephalopathy, early infantile, 9 (EIEE9) characterized by seizures associated with cognitive and behavioral deficits." (PMID 32880860, 2020). "Pcdh19 is a δ2-pcdh and mutations in human PCDH19 cause a female-limited form of early onset epileptic encephalopathy." (PMID 31061071, 2019). "Interestingly, a similar substitution, p.Asp377Glu, has already been described for PCDH19, and it has been shown to impair PCDH19 function and cause early infantile epileptic encephalopathy." (PMID 34244665, 2021). "However, we observed that development prior to the onset of seizures was delayed for 15% of individual,s indicating that PCDH19 mutations produced a developmental encephalopathy, as well as an epileptic encephalopathy in some cases." (PMID 29892053, 2019). "Finally, mutations in PCDH19 can cause an early and severe epileptic encephalopathy mimicking DS, a major problem for differential diagnosis." (PMID 19214208, 2009). "Protocadherin-19 (PCDH19)-Clustering Epilepsy (PCE) is a developmental and epileptic encephalopathy caused by loss-of-function variants of the PCDH19 gene on the X-chromosome." (PMID 38638299, 2024). "Febrile-associated epileptic encephalopathy is a large genetically heterogeneous group that is associated with pathogenic variants in SCN1A, PCDH19, SCN2A, SCN8A, and other genes." (PMID 35711923, 2022). "PCDH19 mutations cause epileptic encephalopathy in humans, but the underlying pathophysiology is not completely understood." (PMID 34272258, 2021). "Although the clinical features of PCDH19-DS patients were slightly different from the classical SCN1A-DS patients, their results demonstrated that PCDH19 was involved in epileptic encephalopathies clinically overlapping with DS." (PMID 22848613, 2012). "Genetic testing of PCDH19 may be useful for all patients with Dravet-like epileptic encephalopathy who have a negative test for SCN1A." (PMID 38891919, 2024).
Cognitive impairment (19 papers, 2009 to 2026). Abnormal cognition is characterized by deficits in thinking, reasoning, or remembering. "The overexpression of miR-21-3p correlates with the inhibition of critical neuronal and synaptic genes such as DLGAP1, which decreased the expression of Protocadherin-19 (PCDH19), associated with cognitive impairment." (PMID 40728960, 2025). "Developmental and epileptic encephalopathy-9 (DEE9) is characterized by seizure onset in infancy, mild to severe intellectual impairment, and psychiatric features and is caused by a mutation in the PCDH19 gene on chromosome Xq22." (PMID 38891919, 2024). "The overexpression of miR-21-3p leads to a significant decrease in the expression of protocadherin 19 (PCDH19), which is related to cognitive impairment, and the mutation of PCDH19 will affect ASD." (PMID 36743290, 2022). "Mutations in the X-linked cell adhesion protein PCDH19 lead to seizures, cognitive impairment, and other behavioral comorbidities when present in a mosaic pattern." (PMID 34272258, 2021). "The relevance of PCDH19-Ncad interactions was recently demonstrated by studies on heterozygous female mice with a mutated PCDH19, which documented hippocampal presynaptic dysfunction and cognitive impairments resulting from mismatched interactions." (PMID 35408865, 2022). "Besides, the overexpression of miR-21-3p leads to a significant decrease in the expression of PCDH19, which is related to cognitive impairment, and the mutation of PCDH19 will affect ASD." (PMID 32824515, 2020). "Mechanistically, we found that TBR2 binds to the genomic regulatory sequences upstream and downstream of Protocadherin-19 (Pcdh19), a member of the Cadherin superfamily that has been implicated in female infantile-onset epilepsy and cognitive impairment and regulates its expression." (PMID 31477701, 2019). "The PCDH19 gene (Xp22.1) encodes the cell-adhesion protein protocadherin-19 (PCDH19) and is responsible for a neurodevelopmental pathology characterized by female-limited epilepsy, cognitive impairment and autistic features, the pathogenic mechanisms of which remain to be elucidated." (PMID 29360992, 2018). "In contrast, PCDH19 patients develop infantile seizures with variable cognitive defects and cortical dysplasia." (PMID 40870033, 2025). "Despite performing normally in the novel object recognition test, Pcdh19 mosaic mice displayed some difficulties in the Morris water maze and fear conditioning tests, suggesting hippocampal-dependent cognitive impairment." (PMID 36997609, 2024). "Pcdh19 mosaic mice reproduced subtle autistic traits and cognitive impairment, which characterize a large proportion of DEE9 patients." (PMID 36997609, 2024). "We have identified PCDH19, a new gene on chromosome X, which was recently found in a familial epileptic syndrome known as female-limited epilepsy and cognitive impairment." (PMID 19214208, 2009). "Considering the synapticlocalization of PCDH9, CDH13 and PCDH19, a mismatch in expression could alter the synaptic contactadhesion leading to network dysfunction and cognitive impairment, both of which arefeatures of PCDH19-CE pathology." (PMID 38629124, 2024). "In addition, this animal model will possibly help researchers design and/or preclinically validate future therapeutic approaches to rescue seizures, core and comorbid behaviours related to ASD, and cognitive impairment in PCDH19-CE people." (PMID 35528232, 2022). "While this study was ongoing, PCDH19 was reported to be the causative gene for female-limited epilepsy and cognitive impairment (EFMR), a disorder characterized by seizure onset in infancy or early childhood and cognitive impairment, which is found only in females in multi-generational families." (PMID 19214208, 2009).
autism (16 papers, 2013 to 2025). Persistent deficits in social interaction and communication and interaction as well as a markedly restricted repertoire of activity and interest as well as repetitive patterns of behavior. "MRI has further disclosed altered patterns of brain expansion in children with autism, but a correlation between specific mutations and autism remains to be clarified in PCDH19-related phenotypes." (PMID 38238304, 2024). "In this case study, we describe two PCDH19 variants (NM_001184880.1: p.Arg787Leu and p.Asp1024Asn) in two unrelated male patients clinically diagnosed with autism." (PMID 36980870, 2023). "Reporting further PCDH19 variants in male patients with ASD is important to assess the possible involvement of this gene in autism." (PMID 36980870, 2023). "Identification of the variant in PCDH19 provides a possible molecular diagnosis to this patient and suggests the disturbance of shared pathways in regressive autism and Dravet-like syndrome." (PMID 32722525, 2020). "Lastly, PCDH19 mutations have been reported in a male with autism, a male with Asperger’s syndrome, and two males with ID." (PMID 29892053, 2019). "In humans, mutations in protocadherin-19 (PCDH19) cause a female limited form of infantile epileptic encephalopathy and are associated with an increased incidence of schizophrenia and autism." (PMID 31061071, 2019). "Additionally, in several animal models of Pcdh19 loss of function (i.e., mouse, zebrafish and Xenopus), Pcdh19 loss causes hyperexcitability and autism-like behaviors also in males." (PMID 39834389, 2024). "Reporting further PCDH19 variants in male patients with autism is important to confirm our hypothesis." (PMID 36980870, 2023). "In conclusion, this is the second report of PCDH19 variants in males with autism." (PMID 36980870, 2023). "By performing histological and behavioural studies in female and male animals, we found that PCDH19 signalling in specific brain areas is implicated in neuronal migration, heat-induced epileptic seizures, core/comorbid behaviours related to autism and cognitive function." (PMID 35528232, 2022). "It is possible a loss of PCDH19-mediated cell-to-cell adhesion may contribute to autism-like behaviors in hemizygous Pcdh19 male KO mice." (PMID 31747920, 2019). "In humans, mutations in protocadherin-19 (PCDH19) cause a female-limited form of infantile epileptic encephalopathy, with further work suggesting that PCDH19 is also linked to a broader array of neural disorders, including autism." (PMID 31061071, 2019). "In the future, the generation of male mice with mosaic Pcdh19 deletions will help address the question of whether both mosaic loss and complete loss of PCDH19 result in autism-like behaviors." (PMID 31747920, 2019). "Heterozygous Pcdh19 knockout female mice also showed reduced sociability in the three-chamber test, resembling autism-like behavior." (PMID 41585885, 2025). "In knockout studies on mice, PCDH19 heterozygous females exhibited decreased sociability, thus indicating autism-like features." (PMID 36980870, 2023). "The structural homology, at the basis of grouping protocadherins, particularly that between PCDH10 and PCDH19 that belong to the same δ2 subfamily, further supports a possible and reasonable involvement of the herein-reported PCDH19 in autism." (PMID 36980870, 2023). "Therefore, autism could be the only presenting feature of PCDH19 mutations in hemizygous males." (PMID 36980870, 2023). "A local mosaic of Pcdh19 downregulation resulted in brain development deficits, heat-induced epileptic seizures, autism-related behaviors, and reduced cognitive performance." (PMID 35528232, 2022). "This suggests heterozygous Pcdh19 KO female mice recapitulate the autism-like symptoms of female EFMR patients." (PMID 31747920, 2019).
autism (continued). "Although it remains unclear whether the other symptoms of EFMR also conform to this unique genotype-phenotype relationship, PCDH19 mutant males were recently reported to demonstrate autism-like symptoms." (PMID 31747920, 2019). "This is the first report showing, in genetically modified mice, that autism-like behaviors induced by Pcdh19 mutations are not subject to the same genotype-phenotype relationship observed in epileptic symptoms of EFMR." (PMID 31747920, 2019). "To determine whether male Pcdh19 KO (XLacZ/Y) mice show increased repetitive behavior—another autism-like phenotype—we monitored their rearing and stereotyped grooming behaviors." (PMID 31747920, 2019). "Thus, their abnormal social interaction results and increased repetitive behaviors suggest hemizygous Pcdh19 KO (XLacZ/Y) mice show autism-like behaviors." (PMID 31747920, 2019). "Considering the fact that male patients affected by mosaic PCDH19 mutations also show autism, the induction of autism in a male patient may not require complete loss of PCDH19 in every cell." (PMID 31747920, 2019). "We, therefore, used a Pcdh19 knockout (KO) mouse model to ask whether a complete lack of PCDH19 causes autism-like behaviors." (PMID 31747920, 2019). "Therefore, autism could be the only presenting feature of PCDH19 mutations in hemizygous males in the absence of tissue mosaicism." (PMID 36980870, 2023). "Consistent with the autism observed in EFMR females, we found Pcdh19 heterozygous KO female mice (with mosaic expression of PCDH19) show defects in sociability in the 3-chamber test." (PMID 31747920, 2019). "Some of the genes, such as NCAN and EPHA7, have similar functionality as NRXN1 in mediating neuronal cell interactions, while some other genes, such as PCDH19, CNTN3, CTNNA3, LMX1B, are known autism candidate genes." (PMID 23536886, 2013). "As such, it is hypothesized that the absence of PCDH19 could interfere with the function of other such unidentified binding proteins that are related to autism." (PMID 36980870, 2023). "Furthermore, knockout studies on mice show that PCDH19 hemizygous males with no expression of PCDH19 have autistic features, while PCDH19 heterozygous females exhibit EFMR, including decreased sociability, thus indicating autism-like features as well." (PMID 36980870, 2023).
developmental and epileptic encephalopathy (11 papers, 2021 to 2026). An epilepsy associated with developmental impairment that may be due to either the underlying etiology or the superimposed epileptic activity, or both. "Pathogenic calcium adhesion molecule‐19 (PCDH19)‐related clustering epilepsy (PCE) is a developmental epileptic encephalopathy resulting from loss‐of‐function mutations in the PCDH19 gene on the X chromosome." (PMID 40411400, 2025). "PCDH19 pathogenic variants cause a rare disease characterized by developmental and epileptic encephalopathy (DEE9) known as PCDH19-Clustering Epilepsy (PCDH19-CE)." (PMID 39834389, 2024). "PCDH19, PLCB1, SCN8A, and HCN1 variations were found in Late Infantile Developmental and Epileptic Encephalopathy (LIDEE) patients." (PMID 41153369, 2025). "In one example, the expression of PCDH19 (MIM: 300460), a gene involved in developmental epileptic encephalopathy (MIM: 300088), was 10 times higher in transactivated HDF than that observed in the brain cortex as reported in GTEx8." (PMID 39084224, 2024).
developmental and epileptic encephalopathy, 9 (9 papers, 2018 to 2024). "Mutations in PCDH19 gene, which encodes protocadherin-19 (PCDH19), cause Developmental and Epileptic Encephalopathy 9 (DEE9)." (PMID 36997609, 2024). "Mutations in the X-linked gene PCDH19 (Xq22.1) cause a severe neurodevelopmental disorder known as Developmental and Epileptic Encephalopathy 9 (DEE9, OMIM # 300088)." (PMID 36997609, 2024). "Loss of function in PCDH19, responsible for Developmental and Epileptic Encephalopathy 9, has been reported." (PMID 33352832, 2020). "Furthermore, more than 100 disease-causing variants have been described in PCDH19 (MIM 300460) in developmental and epileptic encephalopathy 9 (DEE9, OMIM 300088), making it one of the clinically relevant genes in epilepsy." (PMID 34244665, 2021). "The PCDH19 c.1682C>T (p.Pro561Leu) and c.1031C>T (p.Pro344Leu) variants are classified as pathogenic mutations (based on multiple consistent submissions and citing articles) and are associated with Developmental and Epileptic Encephalopathy 9 (OMIM#300088) through the ClinVar database." (PMID 38891919, 2024). "PCDH19-Clustering Epilepsy (PCE), formally known as developmental and epileptic encephalopathy-9 (DEE9), is caused by pathogenic variants in Protocadherin-19 (PCDH19), an X-chromosome gene that undergoes random X-inactivation (RXI)." (PMID 38638299, 2024). "Background/Objectives: Developmental and epileptic encephalopathy 9 (DEE9) (MIM #300088) affects heterozygous females and males with somatic pathogenic variants, while male carriers with hemizygous PCDH19 pathogenic variants are clinically unaffected." (PMID 39457436, 2024). "This year represented a turned point for PCDH19 research, as PCDH19 was recognized as the gene responsible for the neurodevelopmental syndrome known as Developmental and Epileptic Encephalopathy 9; DEE9 (OMIM # 300088)." (PMID 33352832, 2020).